TSLP (thymic stromal lymphopoietin)
Description:
[Isoform 1]: Cytokine that induces the release of T-cell-attracting chemokines from monocytes and, in particular, enhances the maturation of CD11c(+) dendritic cells. Can induce allergic inflammation by directly activating mast cells. [Isoform 2]: May act as an antimicrobial peptide in the oral cavity and on the skin.
Tractability: Small molecule: a structure with a bound ligand is known. Antibody: an approved drug acts on it; UniProt places it where antibodies can reach, with high confidence; its Gene Ontology location is reachable by antibodies, with high confidence; UniProt predicts a signal peptide or a membrane-spanning region.
Target class: Secreted protein
Gene: Protein-coding gene on chromosome 5 (111,070,062 to 111,078,026, forward strand). Ensembl gene ENSG00000145777.
Subcellular location: Secreted
Subcellular location (Human Protein Atlas): Golgi apparatus; Vesicles; Predicted to be secreted
Pathways (Reactome):
Immune System: Interleukin-7 signaling
Gene Ontology:
Molecular function: cytokine activity; interleukin-7 receptor binding
Biological process: cell surface receptor signaling pathway via JAK-STAT; cytokine-mediated signaling pathway; interleukin-7-mediated signaling pathway; negative regulation of apoptotic process; positive regulation of cell population proliferation; positive regulation of chemokine (C-C motif) ligand 1 production; positive regulation of chemokine production; positive regulation of cytokine-mediated signaling pathway; positive regulation of granulocyte colony-stimulating factor production; positive regulation of inflammatory response; positive regulation of interleukin-10 production; positive regulation of interleukin-13 production; positive regulation of interleukin-5 production; positive regulation of interleukin-6 production; positive regulation of mast cell activation; positive regulation of receptor signaling pathway via STAT
Cellular component: extracellular region
Genetic constraint (gnomAD): Loss-of-function variants: 13 observed, 14.43 expected, observed/expected ratio (o/e) 0.9, 90% interval 0.58 to 1.43. The synonymous counts are far from expectation, so gnomAD's model fits this gene poorly and the ratio says little. Missense variants: 222 observed, 200.7 expected, observed/expected ratio (o/e) 1.11, 90% interval 0.99 to 1.24. Synonymous variants: 97 observed, 74 expected, observed/expected ratio (o/e) 1.31, 90% interval 1.11 to 1.55.
Homologues: Orthologues: chimpanzee TSLP (93% identical), rat Tslp (40% identical), dog TSLP (37% identical), mouse Tslp (36% identical).
Diseases named in the same sentence as TSLP in open-access papers:
TSLP is named in the same sentence as 268 diseases in open-access papers, as found by Europe PMC text mining. Sharing a sentence is not in itself a finding about the gene and the disease. The quoted sentences say what the papers report.
asthma (662 papers, 2008 to 2026). "Obesity-driven upregulation of cytokines like IL-25 and TSLP in airway epithelium has also been implicated in asthma onset and progression." (PMID 40998975, 2025). "Only one included study in the systematic review assessed expression of sfTSLP and lfTSLP using RT-PCR; however, it examines the association of TSLP expression with TSLP SNPs and impact on asthma prevalence." (PMID 41357156, 2025). "During RSV infection, the activation of the uric acid pathway increases the expression of TSLP, which in turn activates ILC2s to produce IL-13, promoting a Th2-type immune response associated with the development of asthma." (PMID 40636260, 2025). "Polymorphisms in genes for alarmins (TSLP and IL‐33) and type 2 cytokines (IL‐4 and IL‐13) influence asthma risk and severity, although many genetic contributors remain unidentified." (PMID 40679787, 2025). "Because of its relevant pathogenic features, TSLP is a very suitable molecular target for biologic treatment of severe asthma." (PMID 41321706, 2025). "The aim of this narrative review is to provide an overview of the pathogenic involvement of TSLP in asthma, followed by an updated discussion focused on the therapeutic effects induced by tezepelumab in severe asthmatic patients." (PMID 41321706, 2025). "Tezepelumab is a human IgG2λ mAb that binds to TSLP, a cytokine derived from epithelial cells that is linked to the pathophysiology of various asthma phenotypes, with a high affinity." (PMID 40746413, 2025). "Serum TSLP is independently associated with clinical remission in Th2-high pediatric asthma, though its standalone predictive accuracy is moderate (AUC=0.59)." (PMID 40503233, 2025). "Overall, current evidence demonstrates that TSLP is strongly associated with the pathogenesis of asthma, driving and enhancing the inflammatory response through multiple targets." (PMID 40723867, 2025). "We also have highlighted the need for further studies with larger longitudinal studies including Th2-low asthma cohorts to validate the prognostic utility of TSLP and refine its role in biomarker-guided risk stratification." (PMID 40503233, 2025). "Although the T2low endotype has been shown to be linked to Th1/Th17 responses, an intriguing recent finding was that the alarmin TSLP, initially linked to T2high asthma, was also present in the airways of T2low asthma patients." (PMID 41145900, 2025). "The association between plasma TSLP concentrations with asthma status and asthma severity is inconsistent, with some studies reporting elevated concentrations of serum TSLP in asthmatic subjects compared with healthy individuals." (PMID 41357156, 2025). "It is also noteworthy that genome-wide association studies have highlighted that some single-nucleotide polymorphisms (SNPs), located inside the TSLP gene, outline variable degrees of susceptibility to asthma." (PMID 41321706, 2025). "This study demonstrates that serum TSLP levels are significantly associated with clinical asthma remission, providing a potential biomarker for disease monitoring." (PMID 40503233, 2025). "For instance, TSLP has been shown to activate downstream inflammatory cascades via NF-κB, with elevated TSLP levels in ovalbumin (OVA)-induced asthma models closely associated with NF-κB nuclear translocation." (PMID 40861437, 2025). "Single-nucleotide polymorphisms that elevate TSLP expression have been associated with increased severity and incidence of asthma and identified in patients with chronic rhinosinusitis." (PMID 41409758, 2025). "Lung-specific overexpression of TSLP induces spontaneous asthma-like inflammation in mice, while TSLPR-deficient mice show suppressed inflammation in acute models." (PMID 41259396, 2025). "Thymic stromal lymphopoietin (TSLP) is an epithelial-derived cytokine implicated in the pathogenesis of asthma." (PMID 41357156, 2025). "TSLP plays an important role in the pathophysiology of asthma with increased levels associated with more severe disease." (PMID 39721985, 2025).
asthma (continued). "Despite its association with asthma remission, our ROC analysis (AUC = 0.5887) indicates that TSLP alone lacks sufficient predictive power." (PMID 40503233, 2025). "Elevated TSLP has been implicated in multiple allergic conditions, including AD, asthma, allergic rhinitis, and FA, making it a promising therapeutic target." (PMID 39860604, 2025). "Certain single-nucleotide polymorphisms (SNPs) in the TSLP locus have been linked to increased asthma susceptibility and upregulated TSLP expression." (PMID 41357156, 2025). "Tezepelumab, a human mAb that blocks thymic stromal lymphopoietin (an epithelium-derived cytokine implicated in the pathogenesis of asthma), has advanced to Phase 3 clinical trials." (PMID 40709930, 2025). "This study adds the genetic perspective of TSLP and aids its positive possibility in the susceptibility of asthma, and thus the requirement of anti-TSLP agent." (PMID 39118763, 2024). "A total of 3121 asthma cases and 3041 controls were evaluated for analysis and concluded that polymorphisms rs2289278 and rs3806933 in TSLP had a significant association with asthma." (PMID 39118763, 2024). "The selected GWAS studies have examined how TSLP gene mutations associate with asthma susceptibility and regulatory immune responses to allergic stimuli." (PMID 38672419, 2024). "For example, IL1RL1/IL18R1, IL33 and TSLP have emerged as important genes associated with the development of asthma." (PMID 39694589, 2024). "This meta-analysis contributes the evidence that the polymorphisms rs2289278 and rs3806933 in TSLP were associated with asthma." (PMID 39118763, 2024). "This review highlights the complex interplay of epithelial-derived alarmins, particularly TSLP, IL-33, and IL-25, in orchestrating the skewed T2 inflammatory phenotype that underlies the pathology in asthma." (PMID 39457624, 2024). "In this study, an increased production of IL-33 and TSLP was associated with increased asthma severity, whereas increased production of pro-inflammatory cytokines was linked to decreased production of IFN-β." (PMID 39694589, 2024). "Elevated levels of TSLP seem to be associated with asthma and atopic dermatitis, which are usually both T2 inflammation-mediated conditions." (PMID 38892164, 2024). "Thymic stromal lymphopoietin (TSLP) is an epithelial-cell-derived cytokine implicated in the initiation and persistence of inflammatory pathways in asthma." (PMID 38255279, 2024). "Tezepelumab blocks thymic stromal lymphopoietin, an epithelial cytokine implicated in asthma pathogenesis." (PMID 39588080, 2024). "TSLP is an epithelial-derived cytokine that initiates potent inflammatory responses implicated in the pathogenesis of severe asthma." (PMID 38469627, 2024). "Mast cell-derived tryptase, which activates Par2, was found to be involved in the secretion of thymic stromal lymphopoietin (TSLP), a cytokine associated with inflammatory dermatoses such as atopic dermatitis and some asthma cases." (PMID 38816842, 2024). "Increased TSLP concentration in asthmatic patients correlates with disease severity and the risk of further asthma exacerbations." (PMID 39457624, 2024). "Several genome-wide and single polymorphism studies have shown that multiple SNPs at the TSLP genomic locus are associated with increased asthma susceptibility in different ethnic backgrounds, sex, and age." (PMID 39118763, 2024). "Further research focusing on the association between TSLP and IL-33 gene polymorphisms and asthma is expected to significantly advance disease management." (PMID 38731070, 2024). "Tezepelumab is a human monoclonal antibody that blocks thymic stromal lymphopoietin (TSLP), an epithelial cytokine implicated in multiple aspects of asthma pathophysiology." (PMID 39588080, 2024). "Genome-wide association studies have also identified several key epithelial-expressed genes and gene networks associated with an increased asthma risk, including TSLP, IL33 and IL1RL1 (an IL-33 receptor)." (PMID 38453256, 2024).
asthma (continued). "Two genome-wide association studies conducted in different populations have shown that rs1837253 single nucleotide polymorphisms (SNP) in the TSLP gene are associated with increased asthma risk." (PMID 38672419, 2024). "Genetic and inheritable factors can contribute to the variable expression of TSLP and the risk and severity of asthma." (PMID 38672419, 2024). "OS can inhibit Th2 differentiation by inhibiting the TSLP and NF-κB pathways, which can reduce the apoptosis and inflammation of airway epithelial cells caused by asthma." (PMID 39334402, 2024). "Exposure to inhaled asthma triggers causes the release of epithelial cytokines (TSLP, IL-25 and IL-33), which promotes both innate and adaptive T2 immune responses." (PMID 38453256, 2024). "Generally, TSLP mediates type 2 immunity at barrier surfaces and has been linked to the widespread allergic and inflammatory diseases of the skin (eczema), airways (asthma), and gut (eosinophilic oesophagitis)." (PMID 38846687, 2024). "This study investigated the relationship between serum IL-33 and TSLP levels and asthma, along with polymorphisms in the IL-33 and TSLP genes and asthma susceptibility." (PMID 38731070, 2024). "Current literature is contradictory about the association between different SNPs of the TSLP gene and asthma development in different countries." (PMID 39118763, 2024). "Several genome-wide and single polymorphism studies have shown that multiple single nucleotide polymorphisms at the TSLP genomic locus are associated with increased asthma susceptibility." (PMID 39118763, 2024). "Researches at a global scale have shown that the common SNPs in the TSLP promoter region associated with a higher risk of asthma are rs1837253, rs3806933, rs2289276, and rs228927811–21." (PMID 39118763, 2024). "The databases of PubMed, Embase, Web of Science, and Google Scholar were searched for studies reporting TSLP polymorphisms and asthma from inception to January 2022." (PMID 39118763, 2024). "In this meta-analysis, 11 research papers were sought to measure the association of single nucleotide polymorphisms in thymic stromal lymphopoietin with asthma." (PMID 39118763, 2024). "TSLP expression is also associated with chymase-positive mast cell infiltration of the airways in patients with asthma." (PMID 38453256, 2024). "Viral and bacterial acute respiratory infections can trigger increased bronchial epithelial expression of TSLP and cause asthma exacerbations." (PMID 39385131, 2024). "Based on the information stated earlier, an important question arises: Are individuals with asthma or atopic dermatitis, characterized by elevated concentrations of TSLP in both inflamed tissues and plasma, more predisposed to developing tumors?" (PMID 38557942, 2024). "Heightened epithelial TSLP production during the onset of viral infection is a suggested cause of virus-induced asthma exacerbations in atopic patients; however, this remains yet to be confirmed and requires further investigation." (PMID 38672419, 2024). "For key cytokine levels associated with asthma in the lung, TSLP/OVA administration led to significant increases of lung CCL17 and IL-13 levels in mice in G2 group relative to G1 group." (PMID 39726595, 2024). "Targeting TSLP and its associated signaling pathways has emerged as an attractive strategy for the treatment of asthma." (PMID 38536788, 2024). "Consistent evidence supports that variation in the TSLP gene (5q22.1) is related to the risk of asthma in children and adults, as well as other allergic diseases." (PMID 38672419, 2024). "The epithelial cell-derived danger signal mediators interleukin-33 (IL-33) and thymic stromal lymphopoietin (TSLP) have emerged as key players in the intricate network of adaptive Th2 immune responses associated with asthma." (PMID 38731070, 2024).
asthma (continued). "The detection of nasal TSLP was associated with the subsequent prescription of maintenance asthma treatment (p = 0.04), montelukast (p = 0.01), and the combination montelukast/inhaled glucocorticosteroids (p = 0.03)." (PMID 36694181, 2023). "A positive relation between TSLP levels and the risk of future asthma exacerbation has also been reported." (PMID 36830972, 2023). "Certain TSLP gene variants have been identified, as outcomes of genome-wide association studies, in individuals with asthma, in particular with the association of TSLP SNP rs1837253 with childhood-onset asthma." (PMID 36830972, 2023). "Genome-wide association studies showed that the TSLP single nucleotide polymorphism (SNP) rs1837253 positively correlated with childhood-onset asthma risk, while the same TSLP SNP was also identified as a susceptibility locus for adult asthma." (PMID 37108740, 2023). "Asthma risk is influenced by the combined effects of TSLP genotype and TSLP expression in the nasal epithelium rather than circulating TSLP." (PMID 37628907, 2023). "Papain is a protease known to cause occupational asthma that also induces asthma-like inflammation in mice via TSLP, IL-33, and ILC2." (PMID 36983043, 2023). "A large epidemiological study reveals that plasma high TSLP levels were associated with current asthma, poor lung function, and even the persistence of asthma attacks and dyspnoea 10 years later." (PMID 37377958, 2023). "In the multivariate analysis, adjusting for potential confounders, the detection of TSLP remained independently associated with chronic asthma treatment prescription (aOR:2.724; CI 1.051–7.063, p:0.04) and with current asthma (aOR:3.41; CI 1.20–9.66, p:0.02)." (PMID 36694181, 2023). "TSLP is an epithelial-cell-derived cytokine, belonging to the alarmins group, which plays a key pathogenic role in asthma by acting as an upstream activator of cellular and molecular pathways leading to type 2 (T2-high) airway inflammation." (PMID 36845128, 2023). "TSLP expression in human BALF was closely associated with neutrophil infiltration, and anti-TSLP therapy has been shown to reduce exacerbations in patients with severe, uncontrolled asthma with lower blood eosinophil and FeNO levels." (PMID 37377958, 2023). "This is highlighted by findings in asthma research, where it was observed that the asthma-associated long TSLP isoform negatively regulates the secretion of IgA, potentially impacting the surveillance of mucosal surfaces detrimentally in this condition." (PMID 37515689, 2023). "Peripheral blood IL-6 has recently been identified as a potential biomarker for adult asthma, and IL-33 is a susceptibility gene for childhood asthma, while TSLP is associated with initiation and persistence of inflammatory pathways in asthma." (PMID 38106417, 2023). "Understanding the dynamic interplay between TSLP and the dysfunctional epithelium provides insights into the mechanisms underlying allergy and asthma pathogenesis." (PMID 37628907, 2023). "TSLP overexpression in the airways of asthmatic patients has been reported, and TSLP polymorphisms are linked to asthma susceptibility." (PMID 35292112, 2022). "Anti-TSLP therapy can significantly reduce the number of eosinophils in blood and sputum in asthma in association with a reduction in bronchial obstruction following allergen exposure." (PMID 35572064, 2022). "Early studies in mouse models demonstrated a necessary and sufficient role for TSLP in the initiation of allergic inflammatory diseases based on transgenic lung-specific expression of TSLP in antigen-induced asthma and similar models in TSLPR-deficient mice." (PMID 36311787, 2022). "Among the studies conducted on the gene polymorphisms of TSLP gene and asthma, several SNPs have been shown to impact the susceptibility to this disease." (PMID 35406669, 2022).